NEXN-AS1 (NEXN antisense RNA 1)
Synonyms: C1orf118; FLJ90637
Gene: Long non-coding RNA gene on chromosome 1 (77,881,348 to 77,889,539, reverse strand). Ensembl gene ENSG00000235927.
Diseases named in the same sentence as NEXN-AS1 in open-access papers:
NEXN-AS1 is named in the same sentence as 2 diseases in open-access papers, as found by Europe PMC text mining. Sharing a sentence is not in itself a finding about the gene and the disease. The quoted sentences say what the papers report.
lung carcinoma (2 papers, 2016 to 2017). "As a result, we found that a novel SNP rs114020893 in the lncRNA gene NEXN-AS1 located at 1p31.1 was significantly associated with lung cancer risk." (PMID 27713484, 2016). "Our finding indicates that SNP rs114020893 of NEXN-AS1 at 1p31.1 may contribute to lung cancer susceptibility." (PMID 27713484, 2016). "SNP rs114020893 of NEXN-AS1 at 1p31.1 might also contribute to lung cancer susceptibility." (PMID 28977863, 2017). "As a result, the secondary structure was remarkably changed with the rs114020893 T > C change, indicating that this SNP may be involved in lung cancer development through alteration of the NEXN-AS1 structure and stability, resulting in the functional alteration of its interacting partners." (PMID 27713484, 2016).
NEXN-AS1 also shares sentences with these, for which no sentence is quoted: atherosclerosis (1 paper).